NBN (nibrin)
Diseases named in the same sentence as NBN in open-access papers (continued):
Sharing a sentence is not in itself a finding about the gene and the disease.
cancer (continued). "A homozygous pathogenic variant in NBN was recently reported in an isolated POI case; however, no heterozygous NBN and ATM variants were reported as POI cause, although they have been associated with cancer predisposition." (PMID 33095795, 2020). "This suggests that mutations in conserved residues of MRE11 are less tolerated than those of RAD50 or NBS1/NBN, possibly because these mutations are not advantageous to cellular transformation or cancer progression." (PMID 33339169, 2020). "NBN is DNA repair family gene, involved in the MRE11/RAD50/NBN complex, with nine variants (rs1805794, rs1805790, rs36226237, rs924, rs376639, rs1061302, rs1063054, rs2735383, rs805794) described as associated with high cancer risk." (PMID 28402931, 2017). "Currently, it is not clear how to use low cancer risk genes in management and risk counseling (NBN, XRCC2, GALNT12, etc.), since recommendations should be based either way on the personal and family history of cancer." (PMID 26484312, 2015). "Low levels of p70-nibrin correlate with cancer incidence and it can be speculated that a contributing factor may be higher oxidative stress." (PMID 22396666, 2012). "However, a convincing identification of the cancer risk spectrum associated with germline NBN variants is still lacking and the large studies/meta-analyses including the populations with increased prevalence of germline NBN variants will be of high importance." (PMID 36982687, 2023). "Finally, cancer gene panel testing revealed additional pathogenic variants in two other (non-LS) genes, MC1R and NBN, that are independently associated with elevated risks of cancer in the branches of Family C that did not carry either MMR variant." (PMID 36612224, 2022). "Thus, the members of these branches received negative test results for the familial LS-causing pathogenic variants but some members nevertheless had elevated cancer risks due to the finding of one or both MC1R and NBN variants, for which they were appropriately counseled." (PMID 36612224, 2022). "Hence, although both patients do not show clinical features of a NBS, the NBN variants might confer increased cancer susceptibility." (PMID 33840814, 2021). "The most frequently amplified genes across the pan-cancer atlas were BRIP1 (HDR, 8.04%), POLB (BER, 6.54%), MUS81 (HDR, 6.42%), NBN (HDR, 6.31%), and EXO1 (MMR, 6.26%), while the most frequently deleted genes were BRCA2 (HDR, 6.44%), XRCC2 (HDR, 6.38%), and CUL5 (NER, 6,28%)." (PMID 36081518, 2022). "Firstly, we evaluated the mRNA expression of six DDR-related genes in NSCLC tissues in GEPIA, which demonstrated that CDC25C, NEIL3, H2AFX, NBN, XRCC5 and RAD1 were all significantly higher expressed in NSCLC cancer tissues compared to with normal lung tissues." (PMID 36408135, 2022). "In addition, the cancer genome atlas (TCGA) database was interrogated for alterations in: 1) ATM, MRE11A, RAD50 and NBN; 2) ATR, ATRIP and TOPBP1; and 3) 15 FA genes." (PMID 26438152, 2015). "Of patients who did not have a positive family history of any cancer (n = 487), 57 deleterious variants were detected in 54 patients, including BRCA2 (40.4%, 23/57), BRCA1 (22.8%, 13/57), PALB2 (10.5%, 6/57), NBN (5.3%, 3/57), MRE11A (5.3%, 3/57) and other genes (15.8%, 9/57)." (PMID 36232564, 2022). "Previous studies in cancer cells not treated with chemotherapeutics have shown that the interaction between MDM2 and NBN inhibits the repair of DSBs generated during DNA replication in rapidly proliferating cells." (PMID 34572735, 2021).
tumor (48 papers, 2009 to 2026). "Furthermore, deficiencies in CHEK2, FANCC, or NBN have been shown to induce PARPi sensitivity in other tumor models." (PMID 33339368, 2020). "One publication showed an association between NBN mutations and high-grade PCA in a Polish patient cohort, suggesting a tumor-suppressive function in this gene in normal prostate tissue." (PMID 36139600, 2022). "Here, we review the molecular features and hereditary tumor risk associated with several moderate-penetrance genes in EOC that are involved in the homologous recombination repair pathway, i.e., ATM, BRIP1, NBN, PALB2, and RAD51C/D." (PMID 36233090, 2022). "The palindromes that are associated with oncogenes, such as RAD21, NBN and KMT2A, were found to have changed significantly in the tumor samples." (PMID 33298903, 2020). "Significant associations were also observed for MSH3 rs26279, MSH4 rs5745325, NBN rs1805794, and tumor histotype." (PMID 32957448, 2020). "Surprisingly, we also found that there were partial losses of certain oncogenes (FGFR1, PDGFRA, and so on) and amplifications of certain tumor suppressors (NBN, EXT1, and so on) in these cell lines." (PMID 29880898, 2018). "Nuclear NBN expression was observed in tumours of all patients (Figure 5B3); two tumours also showed cytoplasmic staining." (PMID 25026297, 2014). "Comparing APE1, PTEN, NBN, and PMS2 expression in grade 2, 3 and 4 tumours only PTEN expression was associated grade, with increasing grade being associated with increasing levels of PTEN expression (p=0.004)." (PMID 25026297, 2014). "With respect to MB, not only has it been sporadically described in NBS patients, but heterozygous germline or somatic NBN, RAD50 and MRE11 mutations were discovered in MB patients, implying their potential role as haploinsufficient tumour suppressors for MB development." (PMID 35839783, 2022). "RAD21, BOP1, POLR2E, and PRKDC were mainly expressed in tumor cells, RIPK2 was mainly expressed in monocytes, MAP2K2 was mainly expressed in tumor cells and macrophages, NBN was mainly expressed in macrophages and monocytes, and GPX4 was mainly expressed in tumor cells and T cells." (PMID 36212155, 2022). "For this reason we were able to identify two additional tumor cases with mutations in other DNA damage response genes than BRCA1/2 (PALB2 and NBN), which might also respond to PARP-inhibitor therapy." (PMID 31029168, 2019). "BRCA1, BRCA2 and NBN act as classical tumor suppressor genes." (PMID 31614901, 2019). "In the same tumor sample a germline deleterious mutation in the DNA repair NBN gene was also detected; unfortunately, this was the only sample with defective NBN associated with complete response and no conclusion can be drawn." (PMID 30518089, 2018). "The methylation of the MLH3 promoter, the deletion of the NGR3 and NBN genes or chromothripsis on 13q observed in our study are potential phenomena that might influence tumor cell behavior and thus modulate the tumor’s responsiveness to treatment." (PMID 26865861, 2016). "This suggests that NBN is a haploinsufficient tumour suppressor gene." (PMID 22373003, 2012). "Thus, it has been hypothesized that in cells of carriers of deleterious mutations in DNA repair genes such as NBN, a decrease in DNA repair capabilities resulting from a gene dosage effect (i.e. lower gene expression) may be sufficient to create a permissive environment for tumor development." (PMID 19523210, 2009). "Among these genes, CDC25C, NEIL3, H2AFX, NBN, XRCC5 and RAD1 were all validated to be upregulated in NSCLC tumor tissues." (PMID 36408135, 2022). "Thus, further works could be directed to identify the role of dying tumor cell-derived exosomal hsa_circ_0002130 in potentiating tumor repopulation via promoting DNA damage repair, which was deduced to be mediated by the hsa_circ_0002130/hsa_miR_4482-3p/NBN axis." (PMID 32727565, 2020).
tumor (continued). "The data presented above provides evidence that APE1, NBN, PMS2, MGMT and PTEN mRNA expression levels have prognostic and predictive significance in adult tumours." (PMID 25026297, 2014). "The data presented in adult tumours provide compelling evidence for the role of APE1, NBN, PMS2, MGMT and PTEN in gliomagenesis." (PMID 25026297, 2014). "Furthermore, we confirmed three genes (ATM, NBN and MCPH1) to be downregulated in clinical CRPC tumor samples in our in vitro models." (PMID 36139600, 2022). "Besides, we also observed that MSH4, NBN, NEIL2, OGG1 and XRCC2 were downregulated in both HPV-positive tumor cell lines when compared to the HPV-negative one." (PMID 30674977, 2019). "We identified somatic mutations in NBN, p.P6S, and PAX8, p.R49H, in the LN metastasis; however, we did not identify these mutations in the primary tumor." (PMID 29535844, 2018). "Assessment of individual tumor‐level data indicates that HR alterations are not mutually exclusive, and the most frequently altered HR gene is NBN (22%), while BRCA1 and BRCA2 are altered in ~ 7 and 8% of these tumors, respectively." (PMID 30467127, 2018). "Nine cases with germline variants in HR-related genes PALB2, BRCA1, RAD51C, FAN1 and CHEK2 also showed evidence of enrichment of the germline variant in the tumor, while the other 12 cases with HR-related gene variants (seven FAN1, three CHEK2, one BRIP1, one NBN) did not." (PMID 33917078, 2021). "Importantly, BC arising in CHEK2, NBN/NBS1 and BLM heterozygotes usually demonstrates retention of the wild-type allele in the tumor, therefore there is no ground to expect selective chemosensitivity in these tumor types." (PMID 27555886, 2016). "Immunohistochemistry and immunofluorescence analysis showed that CDC25C, H2AFX, NBN, XRCC5 and RAD1 had positive strong expression in NSCLC tumor tissues and negative weak staining in normal lung tissues and mainly distributed in nucleus and cytoplasm." (PMID 36408135, 2022).
hematological disease (1 paper, 2024). "Intriguingly, in comparison to the previous analysis, we observed 6 new non-synonymous SNVs linked to hematological disease, including variations in CBL (1 pt); DNMT3A (3 pts); FLT3 (1 pts), NQO1 (1 pt); NRAS (1 pts) and 2 frameshifts: CEBPA (1 pts) and NBN (1 pts)." (PMID 38612443, 2024).
NBN also shares sentences with these, for which no sentence is quoted: ataxia-telangiectasia-like disorder (5 papers); lung carcinoma (4); hereditary cancer syndromes (3); Bloom syndrome (2); breast (2); chordoma (2); colon cancer (2); genetic disease (2); juvenile polyposis syndrome (2); Li-Fraumeni syndrome (2); neurofibromatosis type 1 (2); Peutz-Jeghers syndrome (2); triple-negative breast carcinoma (2); acute myeloid leukaemia (1); adenoma (1); aggressive (1); airway hyperresponsiveness (1); aneuploidy (1); angiosarcoma (1); aplastic anemia (1); atypical teratoid rhabdoid tumor (1); bone marrow failure (1); brain tumour (1); childhood cancer (1); COVID-19 (1); cutaneous melanoma (1); dementia (1); desmoplastic melanoma (1); DICER1 syndrome (1); ductal carcinoma in situ (1).
A further 37 diseases each share a sentence with NBN in 1 paper.